RAD51 (RAD51 recombinase)
Diseases named in the same sentence as RAD51 in open-access papers (continued):
Sharing a sentence is not in itself a finding about the gene and the disease.
breast cancer (continued). "RAD51 has proved to be a predictive marker to therapeutic responses in various cancers, including platinum-based chemotherapy benefit in breast cancer, esophageal squamous cell carcinoma, PARP inhibitor benefit in pancreatic cancer and prostate cancer." (PMID 38607586, 2024). "BRCA2 (breast cancer 2, early onset) is one of the main mediators of RAD51 that activates RAD51 nucleofilament formation on ssDNA in HR and on replication forks." (PMID 37439366, 2023). "Previous studies have demonstrated that the small molecule compound B02 inhibits the activity of RAD51 and sensitizes breast cancer cells to DNA‐damaging agents." (PMID 36262061, 2023). "FFPE-based RAD51 assays have previously been described in breast cancer samples, epithelial ovarian cancer and ovarian/endometrial cancer sample cohorts, but never for advanced HGSC specifically." (PMID 36805632, 2023). "Utilizing small molecules R1-1 and B02 to inhibit RAD51, which plays an important role in homologous recombination, has led to radiotherapy and chemotherapy sensitization in glioma and breast cancer, respectively." (PMID 37457440, 2023). "As a positive control for this assay, we used an HR-proficient mammary tumor derived from the K14cre;Trp53F/F (KP) model and observed the highest accumulation of RAD51 foci 2 h after induction of DNA damage." (PMID 37209095, 2023). "In ovarian and breast cancer experimental models, including ex vivo cultures derived from ascites or solid HGSOC, decreased DNA damage-induced nuclear RAD51 foci have been associated with BRCA1 or BRCA2 gene deficiencies and PARPi responses." (PMID 36836518, 2023). "RAD51 focus formation has been described to predict response to chemotherapy in breast cancer patients." (PMID 37029129, 2023). "Three HCR mutations (A1108G, S1114P, and T1115P) found in canine mammary tumors or human breast cancers influenced the RAD51-interaction activity of BRC repeats." (PMID 36851449, 2023). "Rad51 is overexpressed in mammary carcinomas, and this is related to metastases in lymph nodes in both humans and dogs." (PMID 37655260, 2023). "To validate RAD51 inhibition as an appropriate strategy to sensitize bCSCs to treatment such as cisplatin, we performed a preclinical assay using three breast cancer PDXs (CRCM434, CRCM404, and CRCM436)." (PMID 35110528, 2022). "Apart from rare mutations, several common single nucleotide polymorphisms (SNPs) in various HRR genes, including NBN, RAD51, and XRCC3, were reported to affect DNA repair capacity and were previously associated with altered breast cancer risk." (PMID 36139526, 2022). "Some reports have suggested that overexpression of RAD51 induces radioresistance in human cancer tissues and enhances metastasis in human breast cancer cell lines." (PMID 36548864, 2022). "Studies have proven that Rad51 is highly expressed in a range of solid tumors, such as colorectal cancer, breast cancer, prostate cancer, and pancreatic cancer." (PMID 35332852, 2022). "For example, low RAD51 expression correlated with high histologic grade in breast cancer but was predictive of higher complete pathologic response rates to neoadjuvant chemotherapy." (PMID 35626165, 2022). "We examined the relationship between RAD51 expression and radiosensitivity in mammary tumor cell lines." (PMID 36548864, 2022). "No studies have investigated the radiosensitivity and DNA damage repair mechanisms of canine mammary tumor cell lines by focusing on RAD51 expression profile." (PMID 36548864, 2022). "In this manuscript we investigated recombinase RAD51 for its genomic impact as well as its association with clinical outcome in solid tumors including esophageal adenocarcinoma (EAC) and colon and breast cancers." (PMID 36428789, 2022). "The univariate and multivariate Cox regression analysis revealed that six CDM genes (SRF, RAD51, PMF1, EXOSC3, EXOC1 and TSEN54) were associated with the survival of patients with breast cancer." (PMID 35096059, 2022).
breast cancer (continued). "XRCC3 forms a functional complex (the CX3 complex) with another RAD51 paralog, RAD51C, whose LoF events are also mainly caused by gene silencing, in this case in breast cancer samples." (PMID 36969741, 2022). "Relative to three normal cell types, both RAD51 and pRPA32 were overexpressed in gastrointestinal as well as breast cancer cell lines." (PMID 36428789, 2022). "Breast cancer driver gene BRCA2 directed the binding of RAD51 recombinase to single-stranded DNA, reduced the binding of RAD51 to duplex DNA, and stimulated RAD51-mediated DNA strand exchange." (PMID 38091511, 2022). "For instance, B02 ((E)-3-benzyl-2-(2-(pyridin-3-yl) vinyl) quinazolin-4(3H)-one), a specific small chemical inhibitor against Rad51, increases the killing effect of chemotherapeutic agent cisplatin on breast cancer cells." (PMID 35220392, 2022). "As a secondary aim, we evaluated the association of NBN, RAD51 and XRCC3 SNPs with tumor differentiation grade and occurrence of a new primary tumor after longer follow-up in patients with early HER2-positive breast cancer." (PMID 36139526, 2022). "Ovarian and breast cancer susceptibility (BRCA) genes which are mutated in a small subset (<1–7%) of these cancers, have been shown to coordinate with RAD51 to facilitate HR process." (PMID 36428789, 2022). "In the present study, we evaluated the association of tag SNPs in HRR genes NBN, RAD51 and XRCC3 with toxicity and outcome of adjuvant RT and tumor differentiation grade in early HER2-positive breast cancer patients." (PMID 36139526, 2022). "RAD51 overexpression is observed in several human malignancies, including pancreatic adenocarcinoma, non-small-cell lung cancer and breast cancer." (PMID 35646698, 2022). "In breast cancer and liver cancer, the role of RAD51 as a biomarker for immune cell infiltration has been reported." (PMID 35359409, 2022). "The prognostic value of RAD51 has been reported in colon cancer, pancreatic cancer, breast cancer, and liver cancer." (PMID 35359409, 2022). "This interaction between GFP-RB and myc-RAD51 was also observed in the ER+ breast cancer cell line MCF-7 and the TNBC cell line MDA-MB-231." (PMID 34932500, 2022). "Synthetic lethality accompanied by decrease in RAD51 foci was also observed in cells depleted of RAD52 and the other breast cancer susceptibility gene, BRCA1." (PMID 36107942, 2022). "The highest RAD51 expression was observed in triple-negative breast cancer, the most aggressive breast cancer subtype, compared to all other immunohistochemical breast cancer subtypes." (PMID 36139526, 2022). "For instance, miR-155 binds with the 3’-untranslated region (3’-UTR) of Rad51 to regulate DNA repair capability and response to irradiation in breast cancer." (PMID 35875146, 2022). "Amplification and overexpression of RAD51C (a paralog of RAD51) has also been demonstrated in breast cancer cell lines including MCF-7 and a subset of primary breast cancer samples." (PMID 36428789, 2022). "Six CDM genes (SRF, RAD51, PMF1, EXOSC3, EXOC1, and TSEN54) were found to be associated with the prognosis of breast cancer samples." (PMID 35096059, 2022). "Canines have a high incidence of mammary tumors, and several mutations have been detected in BRCA2 and RAD51." (PMID 36548864, 2022). "C-terminal binding protein 1 (CtBP1), a transcription corepressor, confers breast tumor cells resistance to cisplatin by Rad51 upregulation in both breast cancer and gastric cancer cells." (PMID 35875146, 2022). "Survivin has been shown to downregulate members of the HR pathway such as BRCA2 and RAD51 in breast cancer." (PMID 35563522, 2022). "Studies have shown that targeted small-molecule IBR2 can interfere with RAD51, accelerate the degradation of RAD51 protein, thus damage HR, induce apoptosis of breast cancer cells, and provide a new treatment of HER2-negative breast cancer." (PMID 35311116, 2022).
breast cancer (continued). "We selected two cell lines with low and high RAD51 expression from eight mammary tumor-derived cell lines." (PMID 36548864, 2022). "Breast cancer susceptibility genes 1 and 2 (BRCA1 and BRCA2) enable DNA repair protein RAD51 homolog 1 (RAD51) recombinase to displace RPA and stabilize RAD51-single-stranded DNA filaments." (PMID 35572596, 2022). "For instance, first found in breast cancer, the product of the breast cancer-associated gene 2 (BRCA2) mediates the chaperoning of RAD51 onto replication protein A (RPA)-coated ssDNA, thereby promoting cancer development." (PMID 35359409, 2022). "Treatment of EAC, colon and breast cancer cell lines with a small molecule inhibitor of RAD51 inhibited DNA breaking agent-induced DNA breaks and genomic instability." (PMID 36428789, 2022). "CtBP1 (C-terminal binding protein 1) transactivates RAD51 and confers cisplatin resistance to breast cancer cells." (PMID 34716319, 2021). "At first, RAD51 foci were determined by immunochemistry (IHC) staining on fixed breast cancer biopsies collected before and 24 h after neoadjuvant treatment with DSB-inducing chemotherapy, and geminin was utilized as the marker of S/G2 phase of the cell cycle." (PMID 34702316, 2021). "In olaparib-resistant BRCA1-deficient breast cancer cells, ionizing radiation (IR) decreased the number of γ-H2AX foci and increased the number of DNA repair protein RAD51 homolog 1 (RAD51) foci compared with the numbers of them in the parental cells." (PMID 35008473, 2021). "In breast cancer, RAD51 is overexpressed due to excessive transcription and reduced methylation of the gene." (PMID 34207556, 2021). "Overexpression of RAD51 is a predictor of a poor outcome in colorectal adenocarcinoma, breast cancer, pancreatic cancer and non-small cell lung cancer." (PMID 34716319, 2021). "Immunohistochemistry of RAD51 foci was demonstrated in formalin-fixed paraffin-embedded (FFPE) samples of breast cancer, and positive RAD51 foci correlated with resistance to platinum or PARPi." (PMID 34722237, 2021). "Studies from our and other groups suggested that VPA can suppress Rad51 activity for the radiosensitization to breast cancer cells." (PMID 33842359, 2021). "In support of this concept, co-treatment of cells with a RAD51 inhibitor sensitizes breast cancer cells to single Olaparib treatment." (PMID 34356606, 2021). "It is found that UCHL3 weakens radiosensitivity in breast cancer cells by deubiquitinating and activating Rad51." (PMID 34575114, 2021). "In a cohort of 13 BRCAMUT breast cancer PDXs treated with olaparib, the baseline proportion of RAD51-high cells was higher amongst PARPi-sensitive tumors in comparison to PARPi-resistant tumors (24% versus 3%, p = 0.0025)." (PMID 34959671, 2021). "RAD51 expression and the rate of RAD51-mediated HR are both elevated in many types of cancer, including breast cancer." (PMID 34504648, 2021). "Activation of the TGFβ pathway was shown to result in reduced expression of ATM, BRCA1 and BRCA2 in BRCA-proficient breast cancer cells, and of RAD51 in lung epithelial cells -resulting in suppression of DNA damage repair." (PMID 34871431, 2021). "Upregulation of BRCA1 and RAD51 impairs the killing effect of DNA-damaging agents on breast cancer cells." (PMID 34511602, 2021). "L939W reduces interaction with BRCA2, RAD51, XRCC3 and decreases double stranded DNA break initiatedhomologous recombination associated with breast cancer susceptibility." (PMID 34092963, 2021). "Studies have found that RAD51 can mediate breast cancer stem cells to develop resistance to PARP inhibitors in TNBC." (PMID 34408776, 2021). "The breast cancer susceptibility proteins BRCA1 (also known as FANCS), BRCA2 (FANCD1), and RAD51 (FANCR) and its paralogs, including XRCC2 (FANCU) and XRCC3, all serve a function in homologous recombination repair (HRR)." (PMID 33625522, 2021).
breast cancer (continued). "In recent years, RAD51 expression has been detected in several types of cancer, including mainly breast cancer, cervical cancer, and ovarian cancer." (PMID 32190537, 2020). "Mechanistically, DAXX bind to the RAD51 promoter thereby repressing the function of RAD51 and resulting in the inhibition of breast cancer metastasis." (PMID 32257110, 2020). "Basal-like breast cancers commonly carry mutations in genes linked with DNA repair mechanisms like BRCA1, BRCA2, or RAD51." (PMID 33261142, 2020). "Together with quinacrine, curcumin binds DNA more efficiently, being able to cause further damage to breast cancer stem cells and preventing their repair by lowering the expression of DDB2, Polβ, Polδ, PolH, Rad51, Fen1, XRCC1, CHK1, and RPA proteins." (PMID 33330091, 2020). "Ionizing radiation decreases both RAD51 and DNA-protein kinase mRNA expression in human breast cancer cells." (PMID 32726912, 2020). "In contrast, RAD51 foci formation was also decreased in lymphoma cells and breast cancer cells treated with curcumin." (PMID 33330091, 2020). "Ferulic acid potentiated the effects of PARP inhibitors on breast cancer cells by reducing the formation of RAD51 foci and lengthening the time that double-stranded DNA breaks remain unrepaired." (PMID 33330091, 2020). "In a study of breast cancer cell lines, prexasertib synergised with the PARPi olaparib by causing S-phase arrest and inhibiting HRR/RAD51 foci." (PMID 32260355, 2020). "The homozygous gene RAD51 GG was found to be most often in breast cancer patients, while RAD51 G172T has the most clinical significance in cervical cancer." (PMID 32190537, 2020). "Induction of RAD51 nuclear foci after neoadjuvant chemotherapy and PARP inhibition can measure the homologous recombination functionality in breast cancer biopsies, with an association to loss of heterozygosity measures of HR deficiency." (PMID 32471999, 2020). "We further demonstrate the heterogeneity of the DNA damage response within BRCA-mutant TNBC in primary breast cancers, with significant correlations between these signatures and RAD51 expression." (PMID 32642648, 2019). "For the main subtypes of breast cancer, expression of RAD51 was increasing, in ascending order, in luminal (n = 566), Her2-positive (n = 37) and triple-negative breast cancer tissues (n = 116) compared with normal tissues (n = 114) (all P < 0.05)." (PMID 31506496, 2019). "Reported DSB repair variants in breast cancer comprise PALB2, NBN, RAD51, ATM, CHEK2, ATR, RAD50, and WRN." (PMID 31658756, 2019). "The result of immunohistochemistry revealed that highly expressed RAD51 was found in breast cancer tissues compared to normal tissues." (PMID 31506496, 2019). "Overall, our results suggested that a high expression of RAD51, which was an oncogenic marker, was related to a poor prognostic outcome of breast cancer including shorter survival of patients and AI-resistance in neoadjuvant setting." (PMID 31506496, 2019). "UALCAN portal was used to evaluate the expression of RAD51 and survival probability based on tumor stage, subtype, and race in breast cancer patients." (PMID 31492187, 2019). "In breast cancer cells, PTEN inhibition represses nuclear translocation of breast cancer susceptibility 1 (BRCA1) and Rad51; this impairs DNA repair resulting in an accumulation of damaged DNA, which contributes to cell senescence." (PMID 30521029, 2019). "Statistically significant correlations were identified between four single nucleotide polymorphisms and the breast cancer risk: XRCC1-Arg399Gln, hMSH2-Gly322Asp, XPD- Lys751Gln and RAD51--4719A/T." (PMID 30728902, 2019). "It is interesting to note that RAD51 is highly expressed in the TNBC subtype compared to other breast cancer subtypes." (PMID 31492187, 2019). "Our study provided evidences that high expression of RAD51 predicted adverse outcomes, including AI-resistance and shorter survival, for patient affected by breast cancer." (PMID 31506496, 2019).
breast cancer (continued). "Higher expression of CDC25C, ERCC6L or RAD51 was related to shorter overall survival in breast cancer or specified ER-positive breast cancer (all P < 0.05)." (PMID 31506496, 2019). "In order to explore the potential role of RAD51 in breast cancer, multiple analyses about clinical relevance were performed with TCGA samples." (PMID 31506496, 2019). "Firstly, overexpression of RAD51 was found in breast cancer compared to normal breast tissue, which facilitated the clinical application by qPCR detection." (PMID 31506496, 2019). "Beyond validating miR-222 overexpression in tamoxifen resistant cells, this is the first demonstration that upregulation of miR-222 increases PARP1 activation and PARPi sensitivity and decreases RAD51 foci formation in breast cancer cells." (PMID 30621214, 2019). "High expression of RAD51 was detected in primary breast cancer tissues compared with normal breast tissues." (PMID 31506496, 2019). "Combined, our results demonstrate that metformin downregulates the cisplatin-mediated increase in RAD51 expression in both breast cancer and normal mammary epithelial cells." (PMID 31640742, 2019). "Further, both African-American and Asian breast cancer patients with high RAD51 levels display reduced survival probability consistent with RAD51 levels contributing to racial disparities." (PMID 31492187, 2019). "This significant difference was confirmed by the expression analysis of RAD51 in primary breast cancer samples (n = 1097) and normal breast samples (n = 114) (P < 10−12)." (PMID 31506496, 2019). "Previously, we reported that HR genes are overexpressed in sphere cultures obtained from cervical cancer cell lines and that RES inhibits the expression of DNA repair genes such as RAD50 and RAD51 in the MCF-7 breast cancer cell line." (PMID 29681946, 2018). "A previous study indicated that melatonin sensitized human breast cancer cells to IR by downregulating the expression of RAD51 and DNA PKcs, proteins involved in DSB repair, compared to irradiated cells only." (PMID 30544713, 2018). "Overexpression of RAD51 proteins has been observed in many cancer cells, such as thyroid carcinoma, breast cancer, pancreatic cancer, and others." (PMID 30319685, 2018). "Loss of heterozygosity (LOH) at RAD51 15q14-15 loci and 6q23-24 at SASH1 loci in breast cancer has been linked to poor outcomes." (PMID 30627325, 2018). "Strikingly, recent studies have indicated that the RAD51 protein is overexpressed in various types of tumors, including those in breast cancer, non-small cell lung cancer, cervical cancer, pancreatic cancer, ovarian cancers, melanoma, and glioblastoma." (PMID 30319685, 2018). "These authors have reported an inhibitory effect of Akt1 overexpression on Rad51 foci formation and HR repair using an HR-reporter assay in normal tissue and breast cancer cells." (PMID 29156644, 2017). "Akt1 has been reported to impair the nuclear localization and foci formation of BRCA1/Rad51 as well as HR repair in normal tissue and breast cancer cells." (PMID 29156644, 2017). "The spatial localization of BRCA1, BRCA2, RAD51, agrees with the known specificity of these genes to breast cancer, and physical or predicted interactions with each other." (PMID 28326099, 2017). "More recently, RAD51C (a RAD51 paralog involved in double-strand break repair) and the RAD51 recombinase have been identified as targets of epigenetic silencing in breast cancer." (PMID 28679371, 2017). "In support of this notion, we found that both RAD51 and BARD1, a component of the BRCA1 breast cancer susceptibility HDR protein complex, readily accumulate at telomeres in Rap1−/− MEFs expressing TRF2ΔB and in WT MEFs expressing TRF2ΔB; L286R." (PMID 26941064, 2016).